CST7 (cystatin F)
Description:
Inhibits papain and cathepsin L but with affinities lower than other cystatins. May play a role in immune regulation through inhibition of a unique target in the hematopoietic system.
Synonyms: CMAP
Tractability: Small molecule: a structure with a bound ligand is known. Antibody: UniProt places it where antibodies can reach, with high confidence; UniProt predicts a signal peptide or a membrane-spanning region; its Gene Ontology location is reachable by antibodies, with medium confidence. PROTAC: its protein half-life has been measured.
Gene: Protein-coding gene on chromosome 20 (24,949,269 to 24,959,928, forward strand). Ensembl gene ENSG00000077984.
Subcellular location: Secreted; Cytoplasm
Gene Ontology:
Molecular function: cysteine-type endopeptidase inhibitor activity; peptidase inhibitor activity; protease binding; protein binding; protein homodimerization activity; endopeptidase inhibitor activity
Biological process: lysosomal protein catabolic process; regulation of antigen processing and presentation; immune response; negative regulation of microglial cell activation; positive regulation of myelination
Cellular component: cytoplasmic vesicle; endoplasmic reticulum; endosome; extracellular region; Golgi apparatus; lysosome; multivesicular body; late endosome; cytoplasm
Genetic constraint (gnomAD): Loss-of-function variants: 17 observed, 14.28 expected, observed/expected ratio (o/e) 1.19, 90% interval 0.81 to 1.74. The upper end of that interval is the gene's LOEUF score, 1.74, which puts it in group 6 of 6, group 1 being the genes least tolerant of losing a copy. Missense variants: 178 observed, 176.25 expected, observed/expected ratio (o/e) 1.01, 90% interval 0.89 to 1.14. Synonymous variants: 71 observed, 66.62 expected, observed/expected ratio (o/e) 1.07, 90% interval 0.88 to 1.3.
Homologues: Orthologues: chimpanzee CST7 (99% identical), macaque CST7 (92% identical), dog CST7 (72% identical), mouse Cst7 (71% identical), rabbit CST7 (70% identical), rat Cst7 (70% identical), pig CST7 (70% identical), guinea pig CST7 (66% identical), tropical clawed frog cst7 (48% identical), Caenorhabditis elegans cpi-1 (19% identical), Caenorhabditis elegans cpi-2 (18% identical), Caenorhabditis elegans K08B4.7 (8% identical). Paralogues in human: CST3 (30% identical), CST6 (28% identical), CST1 (27% identical), CST2 (26% identical), CST4 (26% identical), CST5 (25% identical), CSTL1 (24% identical), CST8 (23% identical), CST9L (19% identical), CST11 (19% identical), CST9 (15% identical).
Diseases named in the same sentence as CST7 in open-access papers:
CST7 is named in the same sentence as 70 diseases in open-access papers, as found by Europe PMC text mining. Sharing a sentence is not in itself a finding about the gene and the disease. The quoted sentences say what the papers report.
Alzheimer disease (9 papers, 2017 to 2024). A progressive, neurodegenerative disease characterized by loss of function and death of nerve cells in several areas of the brain leading to loss of cognitive function such as memory and language. "Cst7 deletion leads to sex-dependent transcriptomic changes in microglia in the AppNL-G-F model of amyloid-driven Alzheimer’s disease (AD)." (PMID 38085657, 2023). "CST7 has been previously reported to increase in Alzheimer’s disease (AD) and as a cytotoxic marker for cytotoxic CD8 T cells in colorectal cancer with a hypomethylation status." (PMID 36846021, 2022). "We next aimed at comparing cystatin F levels in the brain parenchyma of Creutzfeldt-Jakob disease vs. Alzheimer’s disease patients." (PMID 28178353, 2017). "Collectively, these data indicate similar levels of cystatin F levels in brain parenchyma of patients with Creutzfeldt-Jakob disease and Alzheimer’s disease." (PMID 28178353, 2017). "Cst7/cystatin F is upregulated in microglia in murine models of Alzheimer’s disease (AD)." (PMID 38085657, 2023). "Surprisingly, we found no significant increase in cystatin F levels in both cerebrospinal fluid or brain parenchyma of patients with Creutzfeldt-Jakob disease compared to Alzheimer’s disease or non-demented controls." (PMID 28178353, 2017). "Cystatin F levels were not significantly different between patients with Creutzfeldt-Jakob disease and Alzheimer’s disease, both sampled from the frontal cortex and cerebellum, with linear regression analysis indicating a correlation of cystatin F levels in the two regions of the same case." (PMID 28178353, 2017).
amyloid (6 papers, 2020 to 2025). "We found that high levels of the cystatin F dimer protein in blood contributed to amyloid pathology and cognitive deficits as a risk factor in 5XFAD mice." (PMID 38730470, 2024). "In particular, previous use of spatial transcriptomics to investigate Cx3cr1‐dependent deletion of Inpp5d, when crossed with APP/PS1 amyloidosis mice, highlighted an extended gene expression signature associated with plaques and identified CST7 (cystatin F) as a novel marker of plaques." (PMID 39692624, 2025). "As Cst7 expression is limited to the myeloid compartment in the brain, this study primarily tests the role of microglial/border-associated macrophages in amyloid-driven disease." (PMID 38085657, 2023). "Interestingly, two genes (Cst7 and Itgax) identified as being associated with progressive tau pathology in rTg4510 mice were also significantly associated with amyloid pathology in J20 mice." (PMID 32049030, 2020). "These genes, Thy1, Gfap, Tyrobp, Ctsd, Cst7, C1qb, Lyz2, Ctss, Trem2, Mpeg1, Hexb, Cd68, C1qb, C1qa, Ctsz, Grn, Laptm5, B2m, C1qc, Hexa, and Serpina3n, were increased in the 7-month-old 5XFAD model in the cortex and associated with amyloid plaque image patterns." (PMID 38036733, 2023). "We first compiled data from published datasets to show that Cst7 is indeed robustly and consistently upregulated in microglia across numerous amyloid-driven models of AD." (PMID 38085657, 2023). "Together, these data show that Cst7 drives sex-dependent effects on microglial transcriptome in an amyloid-driven mouse model of AD." (PMID 38085657, 2023). "Here, we reveal that Cst7/CF plays a sexually dimorphic role in microglia in an amyloid-driven AD model, acting as a restraint on microglial endolysosomal activity and phagocytosis specifically in female mice, that when absent results in subtle aggravation of Aβ pathology and synapse loss." (PMID 38085657, 2023). "Here, we set out to investigate what, if any, disease-modifying role Cst7/CF may play in an amyloid-driven AD mouse model in both females and males." (PMID 38085657, 2023). "As Cst7 is so robustly upregulated in microglia in amyloid-driven disease and some studies suggest this to be greater in female mice, we next aimed to investigate whether Cst7/CF plays a role in regulating microglia in disease and whether this regulation could be sex-dependent." (PMID 38085657, 2023). "Together, these data suggest that, in females, Cst7/CF negatively regulates phagocytosis but does not affect lysosomal proteolysis or PRR-driven inflammatory cytokine production in microglia from the AppNL-G-F model of amyloid-driven AD." (PMID 38085657, 2023).
Sepsis (5 papers, 2019 to 2023). Sepsis is defined as life-threatening organ dysfunction caused by a dysregulated host response to infection. "Neutrophil-specific CST7 was significantly upregulated in the whole blood of patients with sepsis, and its encoded Cysteine F was involved in regulating the cytotoxicity of natural killer (NK) cells within the tumor microenvironment." (PMID 36527479, 2023). "Two datasets were identified and CST7 was found to be significantly upregulated in neutrophils from sepsis patients compared to those from healthy controls (effect size = 2.3)." (PMID 33868254, 2021). "Given the initial finding that septic plasma induced upregulation of CST7 in neutrophils, we identified datasets comparing purified neutrophils from healthy controls and sepsis patients." (PMID 33868254, 2021). "Subsequent full text searches using Google Scholar revealed that CST7 was identified as a DEG during sepsis in three studies." (PMID 33868254, 2021). "We discovered that the expression of CST7 in whole blood was markedly upregulated in sepsis as well as across a range of bacterial, viral, and sterile inflammatory conditions." (PMID 33868254, 2021). "While NK cells expressed the highest CST7 levels under healthy conditions, there was a significant increase in CST7 expression in neutrophils during sepsis and these cells became the predominant contributor of CST7 expression." (PMID 33868254, 2021). "Thus, we consider that CST7 upregulation in neutrophils is a novel biological finding in the context of sepsis." (PMID 33868254, 2021). "We next examined whether expression of CST7 is modulated in other leukocyte populations during sepsis using one cohort from the previous analysis that also included purified CD8+ T cells, NK cells, CD4+ T cell and monocytes as well as neutrophils." (PMID 33868254, 2021). "Given this neutrophil-specific increase during sepsis, we next sought to determine whether CST7 levels were increased in neutrophils under other inflammatory conditions." (PMID 33868254, 2021). "By using public transcriptome data, we discovered that CST7 expression is robustly increased in neutrophils cultured in vitro in the presence of plasma from sepsis patients and also in the circulating neutrophils of sepsis patients in vivo." (PMID 33868254, 2021). "Having identified CST7 as an upregulated gene in whole blood during sepsis, we sought to determine whether the change was restricted to sepsis." (PMID 33868254, 2021). "Among these, six publications were related to inflammation; however, none of these articles contained the term “sepsis” or linked cystatin F directly to the term neutrophil." (PMID 33868254, 2021). "AKT1, top up- (FKBP5, SORT1, VNN1, and CST7) and downregulated (PRR5L, SH2B3, SULF2, PLEKHO1, and PTPN6) genes in sepsis were validated using RT-PCR." (PMID 33959663, 2021). "Interestingly, this upregulation of CST7 was neutrophil-specific, as its expression was unchanged in NK and CD8+ T cells during sepsis." (PMID 33868254, 2021). "We further confirmed that CST7 expression was significantly increased in neutrophils following stimulation of plasma from patients with severe sepsis compared with those with non-severe sepsis." (PMID 33868254, 2021). "There was no change in CST7 expression in NK cells or CD8+ T cells during sepsis." (PMID 33868254, 2021). "However, in each of these studies CST7 appeared among dozens of other DEGs and none of these studies commented on the biological relevance of CST7 upregulation during sepsis." (PMID 33868254, 2021). "CST7 was expressed lowly in in CD4+ T cells and monocytes and its expression in these cells did not change during sepsis (Data not shown)." (PMID 33868254, 2021).
cervical cancer (4 papers, 2023 to 2025). A primary or metastatic malignant neoplasm involving the cervix. "It identifies CST7, along with IL1B and ITGA5, as three crucial genes that play a vital role in the evolution of cervical cancer." (PMID 39552709, 2024). "By up-regulating CST7 and down-regulating IL1B and ITGA5, cervical cancer cells’ proliferation ability and invasion ability were successfully reduced." (PMID 36969161, 2023). "We then performed cellular experiments to investigate the role of CST7, IL1B and ITGA5 in cervical cancer cells." (PMID 36969161, 2023). "To explore the potential role of IL1b, CST7, and ITGA5 in the immune microenvironment, we downloaded single-cell data of cervical cancer in GEO to validate our results and explore a more precise transcriptional landscape." (PMID 36969161, 2023). "According to Transwell data, the capacity of cervical cancer cells to migrate was dramatically reduced when IL1B and ITGA5 were knocked down and CST7 was overexpressed in comparison to the control group, similarly, the invasive ability of cervical cancer cells was significantly down-regulated." (PMID 36969161, 2023).
cognitive decline (4 papers, 2022 to 2024). "CST7 protein has also been detected as higher levels predicted slower tau accumulation and cognitive decline with a significant sex interaction effect." (PMID 38085657, 2023). "When using change in cognition as an outcome, we found that MERTK and CST7 predicted less pronounced cognitive decline over time in A+T+ individuals after FDR corrections." (PMID 37118533, 2022). "Similarly, higher levels of AXL, MERTK, GAS6, LPL, CST7 and CSF1 predicted slower tau accumulation and/or cognitive decline in the A+T+ group." (PMID 37118533, 2022).
colorectal cancer (4 papers, 2019 to 2022). A primary or metastatic malignant neoplasm that affects the colon or rectum. "In the context of malignancy, increased levels of CST7 have been correlated with a poorer prognosis in liver metastasis following colorectal cancer and with improved survival in the context of pancreatic ductal adenocarcinoma and hepatocellular carinoma." (PMID 33868254, 2021). "Cystatin F was found in several human cancer cell lines, such as glioblastoma, colorectal carcinoma, and lung carcinoma cell lines, but also is overexpressed in tumor tissue of colorectal carcinoma compared to healthy tissues." (PMID 31340550, 2019). "Indeed, up-regulated cystatin F expression in tumour tissue was demonstrated in patients with colorectal cancer, and was even correlated with liver metastasis and worse prognoses." (PMID 33291222, 2020).
COVID-19 (4 papers, 2020 to 2024). A disease caused by infection with severe acute respiratory syndrome coronavirus 2. "Cd274+ and Cst7+ neutrophils were previously observed in the blood sample of COVID-19 patients and associated with disease severity, confirming the clinical relevance of our finding and indicating the importance of this group of neutrophils in understanding COVID-19." (PMID 39414783, 2024). "COVID-19 patients with encephalopathy had significant overexpression of various cytotoxic genes, including PRF1, GZMK, GZMA, GZMB, GNLY, and CST7." (PMID 37848421, 2023). "We found that NKG7, IL32, GZMA, PRF1, CST7, GZMH, and CCL5 were among the top DEG downregulated in CD3+ upon nasal Foralumab treatment of COVID-19 subjects." (PMID 36881624, 2023). "The function of these cathepsins is further regulated by the endogenous inhibitor cystatin F; however, the status of cystatin F and cathepsins in cytotoxic cells in COVID-19 patients has not been evaluated so far." (PMID 33137165, 2020).
liver cancer (4 papers, 2022 to 2025). An epithelial or non-epithelial malignant neoplasm that arises from the liver. "Moreover, in the present study, CST7 was a T cell-related gene associated with liver cancer prognosis." (PMID 34980144, 2022). "Previously, CST7 has also been associated with CD4(+) T cell and CD8 (+) T cell activation in liver cancer." (PMID 39851522, 2025). "The survival analysis showed that the T cell-related genes EOMES, CST7, CD5L, and EMR2 were associated with the prognosis of liver cancer." (PMID 34980144, 2022). "Moreover, it was disclosed that CST7 exhibited significant enrichment in cancer progenitors, liver cancer advancement, tumor evasion and tolerogenicity, late recurrence of liver cancer, and various subclasses of hepatocellular carcinoma." (PMID 39552709, 2024). "CST7 is associated with activation of CD4T and CD8T cells in liver cancer." (PMID 36969161, 2023). "T cell-related RNAs EOMES, CST7, CD5L, has-miR-23b-3p, and has-miR-23a-3p may be associated with the prognosis of liver cancer." (PMID 34980144, 2022). "Moreover, nine activated memory CD4 T cell-related genes were associated with liver cancer prognosis [e.g., eomesodermin (EOMES), glutathione S-transferase (CST7), and adhesion G protein-coupled receptor E2 (EMR2)]." (PMID 34980144, 2022). "In addition, there were 30 CD8 T cell-related genes associated with liver cancer prognosis [e.g., CD5 molecules like CD5L, EOMES, and CST7]." (PMID 34980144, 2022). "The survival analysis revealed that upregulated expression of T cell-related genes including EOMES, CST7, and CD5L indicated the favorable prognosis of liver cancer." (PMID 34980144, 2022). "Upregulated expression of T cell-related genes including EOMES, CST7, and CD5L indicated the favorable prognosis of liver cancer." (PMID 34980144, 2022). "Thus, we speculate that CST7 and CD5L contribute to liver cancer progression." (PMID 34980144, 2022).
Stroke (4 papers, 2020 to 2024). Sudden impairment of blood flow to a part of the brain due to occlusion or rupture of an artery to the brain. "Genes related to cell proliferation (Top2A, Mki67, and Stmn1) and those affiliated with disease-associated microglia (DAM) such as Apoe, Cst7, Clec7a, Lyz2, Lgals3bp, Igf1, and Lpl are prominently expressed during the acute and subacute phases of stroke." (PMID 39633897, 2024). "Genes linked to microglial responses to demyelination, Alzheimer’s disease, and stroke, including Apoe, Lpl, Spp1, Clec7a, and Cst7, are also upregulated." (PMID 39633897, 2024). "In addition, the marker genes of Cd11c microglial cells are highly expressed, including Spp1, Cst7, Csf1, and Lpl, which are microglial cells related to neurodegenerative diseases and stroke injuries." (PMID 37577391, 2023). "As expected, a known marker of activated MG, Cst7, was increased in aged stroke compared to young stroke brain, confirming that MG were more highly activated in aged stroke brains than in young stroke brains." (PMID 36824976, 2023). "Both Cst7 and Tyrobp were increased in cortex and thalamus by two weeks post-stroke, but not by 3 days." (PMID 36824976, 2023).
brain injury (3 papers, 2018 to 2024). Acute and chronic (see also brain INJURIES, CHRONIC) injuries to the brain, including the cerebral hemispheres, CEREBELLUM, and brain STEM. "The expression of CD11c + and CST7 + in microglia has been originally associated with the DAM phenotype associated with degenerative diseases as well as traumatic brain injury." (PMID 36403069, 2022). "Our previous studies have shown adenosine A2A R activation markedly promotes the expression of cystatin F and exacerbates the white matter lesions induced by hypoxic brain injuries." (PMID 29717153, 2018).
lung carcinoma (3 papers, 2019 to 2025). "Conversely, Cystatin F is expressed in many cancer cell lines, especially lung carcinoma, and other cells like immune cells." (PMID 40641363, 2025). "Besides, CCR7, CST7, GPR143, HDAC5, and IDO1 are also related to lung cancer or the MAPK pathway." (PMID 30972101, 2019).
multiple sclerosis (3 papers, 2017 to 2024). A progressive autoimmune disorder affecting the central nervous system resulting in demyelination. "Cystatin F was detected in all CSF samples, with the highest levels observed in samples from the bacterial meningitis groups (p<0.01 compared to dementia and to multiple sclerosis, p<0.05 compared to encephalitis, one-way ANOVA followed by Bonferroni’s post-hoc test)." (PMID 28178353, 2017).